GFAP (glial fibrillary acidic protein)
Diseases named in the same sentence as GFAP in open-access papers (continued):
Sharing a sentence is not in itself a finding about the gene and the disease.
dementia (continued). "Representative images of GFAP immunostaining in the frontal cortex from a 31-year-old male with DS who died from severe COVID-19, compared to the frontal cortex from an individual with DS without dementia and no COVID-19 infection." (PMID 38801558, 2024). "This study suggests that plasma levels of NfL, but not GFAP, may reflect the contribution of co-morbid vascular disease in the brain to dementia." (PMID 37530894, 2024). "Analyses of AT8, an antibody that recognizes phospho-tau (Ser202 and Thr205) showed the same trend in the no-dementia group: GFAP (β = 33.912 and p = 0.235 in HIP; β = 62.732 and p < 0.001 in TCx) and IBA1 (β = 14.442 and p = 0.36 in HIP; β = 16.344 and p < 0.001 in TCx)." (PMID 39554095, 2024). "Although GFAP is not specific for AD, the high accuracy showed in detecting AD pathology and conversion to AD dementia suggest that plasma GFAP could be a useful indicator of the astroglial activation component of the multifaceted pathology in AD." (PMID 33773595, 2021). "Only one recent study described the potential of serum GFAP as biomarker for AD, by showing increased GFAP levels in CSF biomarker-confirmed AD-dementia cases compared to non-diseased controls, which was comparable to our findings and was in line with previous observations in the CSF of AD patients." (PMID 32988409, 2020). "With no detectable associations with CSF levels of GFAP, MCP-1, IP-10 and IL-8 in the AD group we speculate that an induction of YKL-40 levels in AD occurs early and plateaus when dementia symptoms appear." (PMID 26270969, 2015). "The levels of GFAP and vimentin in CSF did not correlate to the extent of astrogliosis or dementia." (PMID 22577599, 2012). "Therefore, astrogliosis, as demonstrated by GFAP levels and the number of vimentin-positive astrocytes, does not seem to contribute to the frontal-type dementia in PDD and DLB." (PMID 22577599, 2012). "Interestingly, the protective APOE2 allele is associated with neither GFAP nor NEFL, suggesting that its protective effect against dementia may follow mechanisms other than astrocytic function." (PMID 40061357, 2025). "Furthermore, we found that plasma GFAP, NfL, and p-tau181 levels could distinguish between dementia and non-dementia but not between CU and MCI." (PMID 40138103, 2025). "The APOE4 effect on GFAP is seen in both middle aged and older participants, and the effect size increases with the number of APOE4 alleles, regardless of whether the participants developed incident dementia." (PMID 40061357, 2025). "Here, we hypothesize that plasma levels of NfL, GFAP, and t-tau, rather than being causally related to SVD, reflect partly similar or overlapping mechanisms that play an important role in the pathogenesis of dementia." (PMID 37530894, 2024). "In addition, plasma phosphorylated tau (p-tau) and amyloid-beta may be more specific to the brain pathology in dementia as compared to plasma NfL, GFAP, and t-tau, but these biomarkers were not available in the present study." (PMID 37530894, 2024). "Furthermore, we showed that the presence of GFAP or vimentin in CSF could not be used as an indicator of astrogliosis or dementia." (PMID 22577599, 2012). "NfL and GFAP concentrations in both blood and CSF were compared between POD and Non-POD groups, further stratifying by dementia status." (PMID 40354379, 2025). "We could further identify several dementia patients with autoantibodies against GFAP and/or astrocytes, which seems an interesting new marker not only for a subacute autoimmune meningoencephalomyelitis, but also for patients with slowly progressing cognitive decline and dementia." (PMID 39050125, 2024). "Therefore, GFAP may not distinguish CNS inflammation from neurodegeneration in dementia." (PMID 37569491, 2023).
dementia (continued). "Tang and colleagues demonstrated that baseline plasma GFAP exhibited a significant negative correlation with Mini-Mental State Examination scores and further served as a predictive factor for the progression from MCI to dementia among patients with PD." (PMID 37475029, 2023). "GFAP expression, measured in cortex using ELISA, was not an independent predictor of dementia in the CFAS cohort, whereas, in contrast, cortical astrogliosis did show a relationship to dementia in the HAAS cohort, which used a larger number of donations and more brain areas." (PMID 37462105, 2023). "We did not have data available on other identified markers of dementia at examination cycle seven to include in our analyses, e.g., phosphorylated tau species such as p-tau181 and p-tau217, neurofilament light chain (NFL), or glial fibrillary acidic protein (GFAP)." (PMID 35563811, 2022). "The potential of phospho‐GFAP or other PTMs as biomarkers for differential dementia diagnosis has not yet been explored, but based on research summarised above, phospho‐GFAP Serine 13 could be a potential FTLD‐specific biomarker test, and citrullinated GFAP may hold promise for AD and/or MS." (PMID 39289040, 2025).
Cognitive impairment (191 papers, 2011 to 2026). Abnormal cognition is characterized by deficits in thinking, reasoning, or remembering. "Beyond the expected association between ATN cascade markers and cognitive impairment, astrogliosis, as reflected by the increase in GFAP levels, seems to play a role in the cognitive profile of AD patients." (PMID 40144018, 2025). "Firstly, it was difficult for us to obtain a clear causal correlation between GFAP and the cognitive impairment due to the cross-sectional study design." (PMID 40421099, 2025). "Research has shown that elevated GFAP levels are closely associated with cognitive decline in patients with AD, particularly among those diagnosed with mild cognitive impairment (MCI)." (PMID 41300737, 2025). "We have additionally shown that persistently raised serum GFAP was associated with postacute cognitive impairment." (PMID 39312956, 2025). "For instance, studies have shown that elevated GFAP levels are associated with neurological symptoms such as fatigue and cognitive impairment in patients recovering from COVID-19." (PMID 40838185, 2025). "The mechanisms underlying the inverse association of serum GFAP levels with cognitive impairment after ischemic stroke are unclear, but several potential pathways have been proposed." (PMID 40421099, 2025). "In the COVID group (n = 53 of 161, R2 = 0.68, P < 0.001), cognitive deficits were associated with symptoms of depression (−0.056 (0.028), P = 0.050), increased multimorbidity (−0.20 (0.083), P = 0.021) and a raised GFAP (−0.0081 (0.0032), P = 0.017)." (PMID 39312956, 2025). "The main goal of this study was to explore alterations in the plasma GFAP, NfL, and p-tau181 levels associated with cognitive impairment in a community-based adult cohort in Shenzhen City, China." (PMID 40138103, 2025). "Studies have shown that persistently elevated serum GFAP levels aftercraniocerebral trauma injury are associated with a higher risk of psychiatricsymptoms, including cognitive impairment and emotional instability." (PMID 39801405, 2025). "The association between increased levels of GFAP and higher cognitive impairment in the AD group are in line with recent studies that posited specific reactive astrogliosis in AD and its correlation with the severity of cognitive impairment." (PMID 40144018, 2025). "Multiple logistic regression and restricted cubic spline were performed to examine the association between GFAP and cognitive impairment." (PMID 40421099, 2025). "Among the individual biomarker models, only plasma GFAP showed an association with cognitive impairment in the CERAD-TS at baseline." (PMID 38994939, 2024). "Plasma GFAP concentrations are elevated in individuals with AD or at risk of developing AD, and the levels apparently correlate with cognitive impairment." (PMID 39448576, 2024). "In DLB, higher GFAP and NfL at baseline were associated with cognitive impairment and predicted faster cognitive decline." (PMID 38830138, 2024). "The association of higher GFAP with faster declines in verbal fluency aligns with prior studies that suggest astrogliosis promotes synaptic dysfunction and subsequent cognitive impairment." (PMID 38689358, 2024). "For example, raised levels of glial fibrillary acidic protein (GFAP) in CSF and plasma have been suggested to be indicative of astroglial involvement, and linked to cognitive impairment in ALS as well as in frontotemporal dementia (FTD) and Alzheimer's." (PMID 38087504, 2024). "Taken together, these findings suggest that additional studies with larger sample sizes and standardized protocols should be explored to determine exactly how useful plasma or serum GFAP can be as a biomarker for COVID-19-associated cognitive impairment." (PMID 36268187, 2022). "Others have reported associations of NF-L, tau protein, and GFAP levels with cognitive impairments in various diseases or in healthy individuals." (PMID 33558486, 2021).
Cognitive impairment (continued). "Celastrol reduced levels of Aβ protein deposition and GFAP in the hippocampus of diabetic rats, thereby improving the cognitive impairment caused by diabetes." (PMID 34193168, 2021). "Although GFAP levels fall immediately after injury, long lasting elevations in GFAP are associated with long-term cognitive impairment in Veterans with TBI." (PMID 35222223, 2021). "Consistent with previous results, learning and memory dysfunction caused by D-gal is combined with the increased GFAP as an indicator of astrocyte activation in hippocampus, suggesting that astrocytes respond to aging-related cognitive impairment." (PMID 27780933, 2016). "Pinocembrin treatment was found to alleviate the cognitive impairments, decrease the neurological scores, diminish neuronal loss in the hippocampus and reduce the number of GFAP-positive cells in the hippocampal CA1 region of the TGCI rats." (PMID 25187841, 2014). "This approach enabled visualization of age-related changes in GFAP immunoreactivity as well as assessment of potential changes in localization of astrocytes associated with aging and cognitive impairment." (PMID 21989322, 2011). "Despite the lack of association of Aβ and pTau-181 with the cognitive composite z score or adjudicated cognitive impairment, increasing levels of both NfL and GFAP were associated with worsening on the composite z score and increased odds of cognitive impairment." (PMID 39913137, 2025). "However, increasing levels of NfL (odds ratio [OR], 1.10; 95% CI, 1.03-1.18) and GFAP (OR, 1.25; 95% CI, 1.10-1.42) were associated with increased odds of cognitive impairment." (PMID 39913137, 2025). "Additionally, as a baseline predictor, GFAP exhibited a significant association with cross-sectional cognitive impairment in the CERAD-TS measure, particularly in amyloid positive participants." (PMID 38994939, 2024). "Plasma GFAP was significantly increased in patients with PD-MCI compared with HCs, demonstrating that cognitive impairment may be associated with elevated GFAP." (PMID 37815899, 2024). "We speculate that NFL and GFAP exhibit a more direct association with cognitive decline, since neurodegeneration and neuroinflammation are deeply linked to cognitive impairment." (PMID 38994939, 2024). "Global cognitive deficit associated with higher serum GFAP and global brain atrophy." (PMID 37151899, 2023). "Hypothetically, upregulation of GFAP would be linked to cognitive impairment in several domains." (PMID 37475029, 2023). "The moderate association between plasma GFAP and parameters of cognitive impairment, including ALS-specific ECAS scores, the BMDB total score, and the scores in tests exploring semantic fluency and constructional praxis, suggest a link with extra-motor cortical areas." (PMID 37762278, 2023). "We tested whether CSF GFAP mediates the association of AD pathophysiology with hippocampal atrophy and cognitive impairment using structural equation modeling." (PMID 35948658, 2022). "Moreover, La Vitola showed that SNCA mutated mice had more pronounced cognitive deficits along with reduced astroglial markers, i.e., glial fibrillary acidic protein (GFAP), normally involved in glial-neurons communications and BBB integrity." (PMID 35408836, 2022). "Higher plasma levels of p-tau217 and GFAP were consistently associated with reduced FA across multiple periventricular white matter tracts, including the corpus callosum, fornix, optic radiations, and posterior thalamic radiations-pathways known to be vulnerable in early cognitive impairment." (PMID 41646322, 2026). "This study aimed to evaluate whether volumetric MRI and serum NfL and GFAP are associated with cognitive impairment and fatigue in clinically stable relapsing-remitting multiple sclerosis (RRMS) and to examine whether the Expanded Disability Status Scale (EDSS) has an added value." (PMID 41998559, 2026).
Cognitive impairment (continued). "Plasma GFAP levels, more accurately than those in CSF, have been shown to distinguish patients with underlying amyloid pathology independently from the severity of cognitive impairment and even in patients with a primary alternative neurodegenerative disorder, such as Lewy Body disease." (PMID 37762278, 2023). "In addition, recent studies have found higher GFAP levels in cerebrospinal fluid and plasma of clinically symptomatic AD patients, and an association between plasma GFAP and a higher burden of WM lesions and degree of cognitive impairment." (PMID 35534858, 2022). "Taken together, our findings reveal that plasma GFAP, NfL, and p-tau181 levels are suitable as screening biomarkers for early cognitive impairment in Chinese adults." (PMID 40138103, 2025). "The study found that individuals with T2DM, particularly those with cognitive impairments, had significantly higher GFAP levels compared to healthy controls." (PMID 41296388, 2025). "Increases in circulating NfL and GFAP have been reported with AD, mild cognitive impairment and acute COVID15,51,52." (PMID 39885359, 2025). "In diabetic models, rats have been reported to exhibit increased protein expression of both GFAP and S-100β; however, reduced GLT-1 expression was associated with an increased risk of postoperative cognitive impairment in diabetic mice." (PMID 41462586, 2025). "Overall, higher concentrations of inflammatory biomarkers MCP-1 and GFAP explained more cognitive impairment and lower balance scores both pre- and postoperatively." (PMID 40538200, 2025). "The more severe the cognitive impairment, the higher the levels of plasma GFAP, NfL, and p-tau181, and alterations in the plasma GFAP, NfL, and p-tau181 content depends on the stage of subjective cognitive function decline (SCD) and MCI." (PMID 40138103, 2025). "Increasing plasma neurofilament light chain and glial fibrillary acidic protein levels are biomarkers of incident cognitive impairment among participants with type 2 diabetes and overweight or obesity." (PMID 39913137, 2025). "This further indicates that the plasma levels of GFAP, NfL, and p-tau181 demonstrate superior performance compared to plasma Aβ1–42 and Aβ1–40 levels and the Aβ1–42/Aβ1–40 ratio in the context of cognitive impairment." (PMID 40138103, 2025). "Only the increase in GFAP and NfL levels over time was a significant predictor of incident cognitive impairment." (PMID 40606939, 2025). "In vivo and in vitro data revealed that PZ-2891 significantly alleviated cognitive impairment and neuroinflammation and reduced typical AD pathological markers, including p-tau, Aβ and GFAP." (PMID 41471360, 2025). "This systematic review revealed only one study that examined the relationship between GFAP, cognitive impairments and type 2 diabetes mellitus." (PMID 41150802, 2025). "Glial fibrillary acidic protein (GFAP) is one of the sensitive biomarkers of brain injury, and elevated GFAP serum is associated with cognitive impairment." (PMID 39346790, 2024). "Further, recent longitudinal studies have assessed the prognostic potential of baseline blood GFAP levels as a predictor of future cognitive decline in cognitively unimpaired individuals and in those with mild cognitive impairment (MCI) due to AD." (PMID 38439065, 2024). "MCI patients show reductions in hippocampal volume and elevated GFAP levels, potentially indicative of cognitive impairment." (PMID 39534430, 2024). "In the 5XFAD transgenic model of AD, we observed greater GFAP levels in the cortex and hippocampus of transgenic mice relative to wild-type prior to the development of cognitive impairment." (PMID 38343809, 2024). "Plasma GFAP levels in AD-converters remain elevated 5-years prior to as well as coincident with the onset of cognitive impairment due to incident AD." (PMID 38343809, 2024).